EGFR (epidermal growth factor receptor)
Diseases named in the same sentence as EGFR in open-access papers (continued):
Sharing a sentence is not in itself a finding about the gene and the disease.
non-small cell lung carcinoma (continued). "As in the recent use of a dual-targeting strategy to target an epidermal growth factor receptor mutation in non-small-cell lung cancer patients by combining two individual drugs (i.e., afatinib and cetuximab), resulting in dramatic inhibition of tumor growth." (PMID 27734947, 2016). "Specific examples include the use of EGFR tyrosine kinase inhibitors in non-small cell lung cancer (NSCLC) with an EGFR mutation, BRAF inhibitors in melanoma harboring BRAF mutations, or imatinib for chronic myelogenous leukemia." (PMID 26848768, 2016). "Mutations identified in the EGF receptor (EGFR) are the tumour-specific biomarkers for non-small cell lung carcinoma (NSCLC)." (PMID 27585820, 2016). "EGFR T790M mutation occurs in half of non-small cell lung cancer (NSCLC) patients with acquired EGFR-TKI (TKI) resistance, based on tumor re-biopsies using an invasive clinical procedure." (PMID 26867973, 2016). "Association between EGFR-mutant status and Erlotinib treatment with all-cause survival among patients diagnosed in 2010 with stage IV non-small cell lung cancer, Patterns of Care." (PMID 27294665, 2016). "The clinical behavior of patients with advanced non-small cell lung cancer (NSCLC) differ between epidermal growth factor receptor (EGFR) exon 19 deletion (Ex19) and EGFR exon 21 L858R mutation (Ex21)." (PMID 27527915, 2016). "Nowadays EGFR mutation assessment has become the standard approach in non-small cell lung cancer management and is available in most countries." (PMID 27215400, 2016). "EGFR mutation has been reported to be a good outcome predictor for patients with non-small cell lung cancer." (PMID 27623437, 2016). "Non-small cell lung cancer with EGFR mutations are particularly sensitive to EGFR TKIs erlotinib and gefitinib, however resistance often occurs within 10–14 months of treatment, frequently due to the acquisition of the EGFR T790M “gatekeeper” mutation." (PMID 27597943, 2016). "Gefitinib and erlotinib are two selective EGFR-TKIs used as therapy for patients with advanced or metastatic non-small-cell lung cancer who carry activating EGFR mutations." (PMID 27655662, 2016). "The tyrosine kinase inhibitors (TKIs) gefitinib, erlotinib and afatinib are effective therapies for non-small-cell lung cancers (NSCLCs) harbouring activating mutations in the epidermal growth factor receptor (EGFR)." (PMID 25758528, 2015). "Tyrosine kinase inhibitors of the epidermal growth factor receptor (EGFR-TKIs) have been reported to exert a significant impact in the treatment of non-small cell lung cancer (NSCLC), particularly in patients harbouring mutations in the EGFR gene." (PMID 25788996, 2015). "Some of the well-established examples on oncogene addiction include amplification of HER2 in breast cancer, mutated EGFR in non-small cell lung cancer, mutated BRAF in melanomas and Bcr-Abl in chronic myeloid leukemia." (PMID 26204491, 2015). "Examples are imatinib or nilotinib resistance in acute myelocytic leukemia and EGFR inhibitor associated resistance in non-small cell lung cancer." (PMID 26036314, 2015). "In clinic EGFR inhibitors gefitinib and erlotinib are widely used in non-small-cell lung cancer patients with EGFR mutations for their dramatic efficacy." (PMID 26220863, 2015). "Gefitinib is a selective EGFR tyrosine kinase inhibitor currently utilized for the treatment of patients with non-small cell lung cancer harbouring activating EGFR mutations." (PMID 26526352, 2015). "One of the best known examples of personalized therapy is the use of tyrosine kinase inhibitors, such as gefitinib and erlotinib, for the successful treatment of non-small-cell lung cancer patients selected based on the specific EGFR mutations." (PMID 25719557, 2015). "In non-small cell lung cancer p.T790M EGFR resistance mutations were detected with an allele frequency of 0.4 – 0.02%." (PMID 25886408, 2015).
non-small cell lung carcinoma (continued). "Over the past decade, molecularly targeted therapies, which block important oncogenic pathways, have made remarkable progress, especially in epidermal growth factor receptor (EGFR) mutation-positive non-small cell lung cancer (NSCLC)." (PMID 26462025, 2015). "More recently, a myriad of other targeted agents, such as erlotinib in EGFR-mutated non-small cell lung cancer and vemurafenib or dabrafenib in BRAF-mutated melanoma among others, have shown success." (PMID 26418953, 2015). "For example, epidermal growth factor receptor (EGFR) mutations or EGFR overexpression can be detected in non-small-cell lung cancer (NSCLC) patients, leading to the aberrant growth, metastasis, and resistance development of cancer cells." (PMID 26312766, 2015). "Non-small cell lung cancer (NSCLC) patients with epidermal growth factor receptor (EGFR) mutations are responsive to EGFR-tyrosine kinase inhibitor (EGFR-TKI)." (PMID 25869210, 2015). "Epidermal growth factor receptor (EGFR) tyrosine kinase inhibitors (EGFR-TKIs) have been used to treat non-small cell lung carcinoma (NSCLC) patients that have EGFR-activating mutations." (PMID 25634113, 2015). "Resistance to the EGFR tyrosine kinase inhibitors (TKIs) gefitinib and erlotinib, often related to Ras or secondary EGFR mutations, is a relevant clinical issue in Non-Small Cell Lung Cancer (NSCLC)." (PMID 26325669, 2015). "In other way, some patients with non-small cell lung cancer become refractory to Epidermal Growth Factor Receptor (EGFR) inhibitors due to an EGFR mutation or MET amplification that arises after treatment with Getifinib and Erlotinib." (PMID 26227631, 2015). "EGFR-TKIs have been widely used in treating non-small cell lung cancers with EGFR mutation-positive." (PMID 25871388, 2015). "EGFR mutation-induced drug resistance has become a major threat to the treatment of non-small-cell lung carcinoma." (PMID 25993617, 2015). "Appropriate epidermal growth factor receptor (EGFR) gene mutation testing is an essential element in selecting non-small cell lung cancer (NSCLC) patients for therapy with tyrosine kinase inhibitors of EGFR (TKIs EGFR)." (PMID 25086987, 2015). "The significant efficacy of tyrosine kinase inhibitors (TKIs) has been approved for advanced non-small cell lung cancer (NSCLC) patients with activating epidermal growth factor receptor (EGFR) mutations." (PMID 26383985, 2015). "The clinical efficacy of EGFR tyrosine kinase inhibitors (TKIs) in non-small cell lung cancer (NSCLC) harbouring activating EGFR mutations is limited by the emergence of acquired resistance, mostly ascribed to the secondary EGFR-T790M mutation." (PMID 26015408, 2015). "Afatinib is a second-generation of epidermal growth factor receptor (EGFR) tyrosine kinase inhibitor and has shown a significant clinical benefit in non-small cell lung cancer (NSCLC) patients with EGFR-activating mutations." (PMID 25714021, 2015). "For example, Gefitinib and Erlotinib have provided clinical benefit in non-small cell lung cancer with activating EGFR mutations." (PMID 25978653, 2015). "Currently epidermal growth factor receptor tyrosine kinase inhibitor (EGFR-TKI) is widely used for treatment of non-small cell lung cancer (NSCLC) patients with EGFR mutation." (PMID 26302350, 2015). "In the management of advanced non-small cell lung cancer, epidermal growth factor receptor (EGFR) mutation testing is routinely used to guide treatment plans." (PMID 26247463, 2015). "Epidermal growth factor receptor (EGFR) mutation-induced drug resistance has caused great difficulties in the treatment of non-small-cell lung cancer (NSCLC)." (PMID 25886721, 2015). "Previous studies showed that gefitinib treatment of non-small cell lung cancer patients with EGFR exon 19 and 21 mutations achieves a dramatic clinical response." (PMID 26392415, 2015).
non-small cell lung carcinoma (continued). "The dysregulation of epidermal growth factor receptor (EGFR) signaling has been well documented to contribute to the progression of non-small cell lung cancer (NSCLC), the leading cause of cancer death in the world." (PMID 26528697, 2015). "Treatment decisions in advanced non-small cell lung cancer rely on accurate analysis of the EGFR mutation status in small tissue samples." (PMID 26022577, 2015). "The tyrosine kinase inhibitor gefitinib has demonstrated survival benefit in EGFR mutated non-small cell lung cancer and cetuximab, an anti-EGFR monoclonal antibody, improves survival in KRAS wild type colorectal cancer." (PMID 26478746, 2015). "Epidermal growth factor receptor (EGFR) tyrosine kinase inhibitors (TKIs) are successfully used in non-small cell lung cancer (NSCLC) patients harboring EGFR-activating mutations." (PMID 25871388, 2015). "We evaluated the prediction value of EGFR mutation status on response to first-line chemotherapy in patients with advanced non-small-cell lung cancer (NSCLC)." (PMID 25800568, 2015). "The prognostic value of Bcl-2-like protein 11 (BIM) deletion polymorphism for epidermal growth factor receptor (EGFR) tyrosine kinase inhibitors (TKIs) treatment in non-small cell lung cancer (NSCLC) were reported." (PMID 26325082, 2015). "Non-small cell lung cancer (NSCLC) with brain metastasis (BM) harboring an epidermal growth factor receptor (EGFR) mutation shows good response to tyrosine kinase inhibitors (TKIs)." (PMID 26014133, 2015). "Analysis of non-small cell lung cancer (NSCLC) patients has shown that 70–80% of EGFR/HER1 gene-mutated patients are responsive to TKIs compared with 10–20% of EGFR/HER1 wild-type patients." (PMID 25674538, 2015). "In particular, EGFR (HER1 or ErbB1) overexpression has been linked to the progression of many human cancers, including head and neck, breast, and non-small-cell lung cancers, making it a primary candidate for targeted therapies." (PMID 25762314, 2015). "Epidermal growth factor receptor tyrosine kinase inhibitors (EGFR-TKIs), including gefitinib, are effective for non-small cell lung cancer (NSCLC) patients with EGFR mutations." (PMID 25807554, 2015). "Epidermal growth factor receptor (EGFR)-tyrosine kinase inhibitors (TKIs) have dramatically changed the prognosis of advanced non-small cell lung cancers (NSCLCs) that harbour specific EGFR activating mutations." (PMID 26435742, 2015). "Tyrosine kinase inhibitors of epidermal growth factor receptor (EGFR-TKIs) are standard treatments for advanced non-small-cell lung cancer (NSCLC) patients harboring activating epidermal growth factor receptor (EGFR) mutations." (PMID 26227959, 2015). "Tyrosine kinase inhibitors (TKIs) have shown strong activity against non-small-cell lung cancer (NSCLC) patients harboring activating epidermal growth factor receptor (EGFR) mutations." (PMID 26247735, 2015). "Tyrosine kinase inhibitors are effective treatments for non-small-cell lung cancers (NSCLCs) with epidermal growth factor receptor (EGFR) mutations." (PMID 25758528, 2015). "Afatinib has recently been approved in several countries for the treatment of patients with a distinct type of EGFR-mutated non-small cell lung cancer." (PMID 24643470, 2014). "For example, the tyrosine kinase inhibitor gefitinib has been shown to be effective in a select group of non-small cell lung cancer patients with epidermal growth factor receptor (EGFR) mutations, providing a 13.5 month improvement of median overall survival." (PMID 25364720, 2014). "The EGFR inhibitor, Erlotinib, is effective in the treatment of non-small cell lung cancer and is associated with increased intratumoral numbers of dendritic cells." (PMID 25089198, 2014). "CD44 variant, NM_001001390 and CEACAM1 variant, NM_000610 are found to be linked to NM_201283 of EGFR, in cancer samples and are also in reported to be critical in non-small cell lung cancers." (PMID 25034693, 2014).
non-small cell lung carcinoma (continued). "Another example is EGFR, where standard treatment guidelines recommend testing for EGFR mutations in patients with non-small cell lung cancer." (PMID 25593991, 2014). "Most patients with epidermal growth factor receptor (EGFR) mutation-positive non-small cell lung cancer (NSCLC) respond to first-line EGFR tyrosine kinase inhibitors, but later acquire resistance." (PMID 25374620, 2014). "In recent years, it has been well known that non-small cell lung cancer (NSCLC) patients with mutations of epidermal growth factor receptor (EGFR) response beter to EGFR-tyrosine kinase inhibitor treatment." (PMID 25248714, 2014). "Epidermal growth factor receptor (EGFR) tyrosine kinase inhibitors (TKIs), such as gefitinib and erlotinib, are known to play a significant role in EGFR mutation-positive non-small cell lung cancer." (PMID 25120716, 2014). "The aim of this study was to assess the role of EGFR mutation subtypes in predicting the efficacy of EGFR tyrosine kinase inhibitors (EGFR TKIs) and the prognosis of patients with advanced non-small cell lung cancer (NSCLC)." (PMID 24908327, 2014). "EGFR mutation detection has been widely applied in the prediction of TKIs therapy in Non-Small Cell Lung Cancer (NSCLC)." (PMID 24398248, 2014). "Several randomized trials have demonstrated non-small cell lung cancer (NSCLC) patients with activating epidermal growth factor receptor (EGFR) mutations can achieve favorable clinical outcomes on treatment with EGFR tyrosine kinase inhibitors (TKIs)." (PMID 25277203, 2014). "Afatinib (also known as BIBW 2992) has recently been approved in several countries for the treatment of a distinct type of epidermal growth factor receptor (EGFR)-mutated non-small cell lung cancer." (PMID 24643470, 2014). "This article briefly reviews the pivotal trials leading to approval of EGFR TKIs in the first-line setting for patients with EGFR mutation-positive non-small cell lung carcinomas." (PMID 25309870, 2014). "Inferred differential cancer networks on well established Bcl-x and EGFR centered networks in non-small cell lung cancer concede with cancer-specific splice variants reported in literature." (PMID 25034693, 2014). "Mutations of EGFR have been identified as a key driving cause in tumorigenesis and progression of non-small cell lung carcinoma (NSCLC)." (PMID 25395181, 2014). "Various studies have assessed the diagnostic accuracy of EGFR mutation-specific antibodies in non-small cell lung cancer (NSCLC)." (PMID 25203004, 2014). "Treatment with tyrosine kinase inhibitors (TKIs) has shown promising results in non-small-cell lung cancer (NSCLC) patients harboring activating epidermal growth factor receptor (EGFR) mutations." (PMID 25561229, 2014). "Differential edges of CD44 variant, NM_001001390 and CEACAM variant, NM_000610 with EGFR-NM_201283 clues their collective role in cancer and are also reported to be critical in non-small cell lung cancers." (PMID 25034693, 2014). "Mutations in EGFR can confer sensitivity or resistance to EGFR tyrosine kinase inhibitors such as gefitinib and erlotinib in patients with advanced non-small-cell lung cancer (NSCLC)." (PMID 24769870, 2014). "Although non-small cell lung cancer (NSCLC) patients with EGFR mutation positive (EGFR M+) tumors initially respond well to EGFR tyrosine kinase inhibitor (TKI) monotherapy, the responses are usually incomplete." (PMID 24946858, 2014). "LUX-Lung 2 evaluated 50 mg/day afatinib in patients with EGFR mutation-positive non-small cell lung cancer who had received ≤1 prior chemotherapy regimen." (PMID 25432788, 2014). "This is exemplified by the development of resistance to EGFR tyrosine kinase inhibitor (TKI), through emergence of a secondary T790M EGFR mutation in non-small-cell lung carcinoma (NSCLC), which occurs in 50% of the patients with lung adenocarcinoma." (PMID 24612546, 2014).
non-small cell lung carcinoma (continued). "The efficacy of epidermal growth factor receptor-tyrosine kinase inhibitor (EGFR-TKI) for treatment of non-small cell lung carcinoma (NSCLC) patients with EGFR activating mutations is well established." (PMID 24396447, 2014). "Tyrosine kinase inhibitors (TKIs) are very efficacious in non-small-cell lung cancer (NSCLC) patients harboring activating Epidermal Growth Factor Receptor (EGFR) mutations." (PMID 25561229, 2014). "Since their first description, activating epidermal growth factor receptor (EGFR) mutations identify a distinct clinical entity of patients with non-small-cell lung cancer (NSCLC)." (PMID 25505694, 2014). "Assessment of EGFR mutation in non-small cell lung cancer (NSCLC) patients is mandatory for optimization of pharmacologic treatment." (PMID 25137181, 2014). "Activating EGFR mutations are well described in non-small cell lung cancer and have been reported in various cancers of the salivary glands." (PMID 25343854, 2014). "Activating epidermal growth factor receptor (EGFR) mutations characterize a subgroup of non-small-cell lung cancer that benefit from first line EGFR tyrosine kinase inhibitors (EGFR-TKI)." (PMID 24885034, 2014). "Several EGFR-tyrosine kinase inhibitors (EGFR-TKIs) including erlotinib, gefitinib, afatinib and icotinib are currently available as treatment for patients with advanced non-small-cell lung cancer (NSCLC) who harbor EGFR mutations." (PMID 24533047, 2014). "Epidermal growth factor receptor mutations appear to identify distinct subsets of patients with an increased response to gefitinib in non-small cell lung carcinoma." (PMID 24959213, 2014). "The detection results of the two EGFR mutations in 45 non-small cell lung cancer samples further supported the applicability of the real-time Bi-PAP." (PMID 24769870, 2014). "With regard to the non-small cell lung cancer, the discordance rates of EGFR mutations vary between 10 and 54%; however, these figures must be interpreted with caution, given the heterogeneity of methods employed in various studies." (PMID 25202344, 2014). "We correlated the expression of hamartin, p-TSC2 and p-mTOR with expression data concerning epidermal growth factor receptor mutations in non-small cell lung cancer and their influence on downstream Akt, MAPK and Stat3 signaling." (PMID 24593867, 2014). "In more recent analyses, an overall survival benefit with afatinib versus chemotherapy was also observed in patients with non-small cell lung cancer harbouring the EGFR Del19 mutation." (PMID 25432788, 2014). "For example, treatment with gefitinib or erlotinib, a TKI for EGFR, causes enhanced apoptosis in several cancer cells in vitro or in xenograft tumor growths from breast cancer patients and EGFR-dependent non-small cell lung cancer (NSCLC) cells, respectively." (PMID 24970817, 2014). "For example, a majority of metastatic non-small cell lung cancer (NSCLC) patients with EGFR-activating mutations respond to treatment with erlotinib; however, all patients ultimately progress." (PMID 25501935, 2014). "The prognostic value of epidermal growth factor receptor (EGFR) mutations in resected non-small cell lung cancer (NSCLC) remains controversial." (PMID 25162713, 2014). "Afatinib, an irreversible ErbB family blocker, was recently approved for the first-line treatment of EGFR mutation-positive metastatic non-small cell lung cancer." (PMID 24973959, 2014). "Our aim here was to elucidate the role of hypoxia and CSCs in the resistance to gefitinib in non-small cell lung cancer (NSCLC) with activating epidermal growth factor receptor (EGFR) mutation." (PMID 24489728, 2014). "It has recently been approved in several countries for the treatment of a distinct type of EGFR-mutated non-small cell lung cancer (NSCLC)." (PMID 24643470, 2014).